TANK (TRAF family member associated NFKB activator)
Description:
Adapter protein involved in I-kappa-B-kinase (IKK) regulation which constitutively binds TBK1 and IKBKE playing a role in antiviral innate immunity. Acts as a regulator of TRAF function by maintaining them in a latent state. Blocks TRAF2 binding to LMP1 and inhibits LMP1-mediated NF-kappa-B activation. Negatively regulates NF-kappaB signaling and cell survival upon DNA damage. Plays a role as an adapter to assemble ZC3H12A, USP10 in a deubiquitination complex which plays a negative feedback response to attenuate NF-kappaB activation through the deubiquitination of IKBKG or TRAF6 in response to interleukin-1-beta (IL1B) stimulation or upon DNA damage. Promotes UBP10-induced deubiquitination of TRAF6 in response to DNA damage. May control negatively TRAF2-mediated NF-kappa-B activation signaled by CD40, TNFR1 and TNFR2.
Synonyms: I-TRAF; ITRAF; TRAF2
Tractability: PROTAC: ubiquitination databases record sites on it; its protein half-life has been measured; a small molecule that binds it is known.
Gene: Protein-coding gene on chromosome 2 (161,136,908 to 161,236,230, forward strand). Ensembl gene ENSG00000136560.
Subcellular location: Cytoplasm
Subcellular location (Human Protein Atlas): Cytosol; Nucleoli
Pathways (Reactome):
Immune System: Activation of IRF3, IRF7 mediated by TBK1, IKKε (IKBKE); Regulation of TBK1, IKKε (IKBKE)-mediated activation of IRF3, IRF7; Regulation of TBK1, IKKε-mediated activation of IRF3, IRF7 upon TLR3 ligation; TICAM1-dependent activation of IRF3/IRF7; TRAF6 mediated IRF7 activation
Gene Ontology:
Molecular function: cysteine-type deubiquitinase activity; deubiquitinase activator activity; molecular adaptor activity; protein binding; ubiquitin protein ligase binding
Biological process: cellular response to interleukin-1; cellular response to ionizing radiation; cellular response to tumor necrosis factor; DNA damage response; negative regulation of canonical NF-kappaB signal transduction; positive regulation of protein deubiquitination; positive regulation of type I interferon production; positive regulation of ubiquitin-specific protease activity; defense response to virus; signal transduction; type I interferon-mediated signaling pathway
Cellular component: cytoplasm; cytosol; nucleolus; protein-containing complex; serine/threonine protein kinase complex
Genetic constraint (gnomAD): Loss-of-function variants: 8 observed, 32.69 expected, observed/expected ratio (o/e) 0.24, 90% interval 0.14 to 0.44. The upper end of that interval is the gene's LOEUF score, 0.44, which puts it in group 1 of 6, group 1 being the genes least tolerant of losing a copy. Missense variants: 348 observed, 439.74 expected, observed/expected ratio (o/e) 0.79, 90% interval 0.72 to 0.87. Synonymous variants: 138 observed, 163.1 expected, observed/expected ratio (o/e) 0.85, 90% interval 0.74 to 0.98.
Homologues: Orthologues: chimpanzee TANK (99% identical), macaque TANK (97% identical), rabbit TANK (88% identical), dog TANK (86% identical), pig TANK (85% identical), guinea pig TANK (82% identical), mouse Tank (79% identical), rat Tank (75% identical), tropical clawed frog tank (33% identical), zebrafish tank (25% identical).